SETDB1 (SET domain bifurcated histone lysine methyltransferase 1)
Description:
Histone methyltransferase that specifically trimethylates 'Lys-9' of histone H3 (H3K9me3). H3 'Lys-9' trimethylation represents a specific tag for epigenetic transcriptional repression by recruiting HP1 (CBX1, CBX3 and/or CBX5) proteins to methylated histones. Mainly functions in euchromatin regions, thereby playing a central role in the silencing of euchromatic genes. H3 'Lys-9' trimethylation is coordinated with DNA methylation. Forms a complex with MBD1 and ATF7IP that represses transcription and couples DNA methylation and histone 'Lys-9' trimethylation. Its activity is dependent on MBD1 and is heritably maintained through DNA replication by being recruited by CAF-1. SETDB1 is targeted to histone H3 by TRIM28/TIF1B, a factor recruited by KRAB zinc-finger proteins. Required for HUSH-mediated heterochromatin formation and gene silencing. Probably forms a corepressor complex required for activated KRAS-mediated promoter hypermethylation and transcriptional silencing of tumor suppressor genes (TSGs) or other tumor-related genes in colorectal cancer (CRC) cells. Required to maintain a transcriptionally repressive state of genes in undifferentiated embryonic stem cells (ESCs). In ESCs, in collaboration with TRIM28, is also required for H3K9me3 and silencing of endogenous and introduced retroviruses in a DNA-methylation independent-pathway. Associates at promoter regions of tumor suppressor genes (TSGs) leading to their gene silencing. The SETDB1-TRIM28-ZNF274 complex may play a role in recruiting ATRX to the 3'-exons of zinc-finger coding genes with atypical chromatin signatures to establish or maintain/protect H3K9me3 at these transcriptionally active regions. Also catalyzes mono- and dimethylation of 'Lys-9' of free histone H3 (H3K9me1 and H3K9me2) during translation in the cytoplasm, which is then transported to the nucleus and incorporated into nucleosomes. [Isoform 2]: Lacks all domains required for histone methyltransferase activity.
Synonyms: ESET; KIAA0067; KMT1E; KG1T; TDRD21; H3-K9-HMTase4
Tractability: Small molecule: a structure with a bound ligand is known; a high-quality ligand is known. PROTAC: UniProt records ubiquitination sites on it; ubiquitination databases record sites on it; its protein half-life has been measured; a small molecule that binds it is known.
Target class: Writer; Protein methyltransferase; SET domain; Epigenetic regulator
Chemical probes: (R,R)-59 (high quality)
Gene: Protein-coding gene on chromosome 1 (150,926,263 to 150,964,744, forward strand). Ensembl gene ENSG00000143379.
Subcellular location: Nucleus; Cytoplasm; Chromosome
Subcellular location (Human Protein Atlas): Nucleoplasm; Vesicles
Pathways (Reactome):
Gene expression (Transcription): Regulation of endogenous retroelements by KRAB-ZFP proteins; Regulation of endogenous retroelements by the Human Silencing Hub (HUSH) complex
Chromatin organization: PKMTs methylate histone lysines
Gene Ontology:
Molecular function: chromatin binding; histone H3K14ac reader activity; histone H3K9 dimethyltransferase activity; histone H3K9 methyltransferase activity; histone H3K9 monomethyltransferase activity; histone H3K9 trimethyltransferase activity; histone H3K9me2 methyltransferase activity; histone H3K9me2/3 reader activity; promoter-specific chromatin binding; protein binding; histone H3 methyltransferase activity; DNA binding; histone methyltransferase activity; zinc ion binding
Biological process: DNA methylation-dependent constitutive heterochromatin formation; heterochromatin organization; negative regulation of gene expression; transposable element silencing by heterochromatin formation
Cellular component: chromatin; chromosome; cytoplasm; nucleoplasm; nucleus; nuclear lumen
Genetic constraint (gnomAD): Loss-of-function variants: 26 observed, 124.47 expected, observed/expected ratio (o/e) 0.21, 90% interval 0.15 to 0.29. The upper end of that interval is the gene's LOEUF score, 0.29, which puts it in group 1 of 6, group 1 being the genes least tolerant of losing a copy. Missense variants: 1,043 observed, 1,602.2 expected, observed/expected ratio (o/e) 0.65, 90% interval 0.62 to 0.69. Synonymous variants: 517 observed, 576.66 expected, observed/expected ratio (o/e) 0.9, 90% interval 0.83 to 0.96.
Cancer hallmarks: proliferative signalling (promotes); invasion and metastasis (promotes); escaping immune response to cancer (promotes); invasion and metastasis (suppresses); cell replicative immortality (suppresses); escaping programmed cell death (promotes)
Homologues: Orthologues: chimpanzee SETDB1 (99% identical), dog SETDB1 (97% identical), pig SETDB1 (96% identical), guinea pig SETDB1 (95% identical), macaque SETDB1 (95% identical), rabbit SETDB1 (95% identical), mouse Setdb1 (92% identical), rat Setdb1 (92% identical), tropical clawed frog setdb1 (69% identical), zebrafish setdb1b (56% identical), Drosophila melanogaster egg (29% identical), Drosophila melanogaster G9a (13% identical), and 16 more. Paralogues in human: SETDB2 (18% identical), EHMT1 (15% identical), EHMT2 (14% identical), KMT2A (11% identical), KMT2C (11% identical), KMT2D (11% identical), KMT2B (10% identical), ASH1L (10% identical), SETD1B (9% identical), NSD1 (9% identical), NSD2 (8% identical), SETD1A (8% identical), and 7 more.
Diseases named in the same sentence as SETDB1 in open-access papers:
SETDB1 is named in the same sentence as 136 diseases in open-access papers, as found by Europe PMC text mining. Sharing a sentence is not in itself a finding about the gene and the disease. The quoted sentences say what the papers report.
melanoma (78 papers, 2011 to 2025). A malignant, usually aggressive tumor composed of atypical, neoplastic melanocytes. "Among these modifications, the lysine methyltransferase SETDB1 has been implicated in melanoma progression." (PMID 40872623, 2025). "SETDB1 has been associated with epigenetic silencing of tumor suppressor genes and has also been implicated in stem cell-like properties, particularly in melanoma, lung carcinomas, and invasive breast carcinomas." (PMID 41503337, 2025). "Frequent amplification of SETDB1 in various tumor types (including melanoma, lung, colon, breast and liver cancers) and SETDB1 deletion-associated defects in tumor growth support its function as a prominent cancer driver." (PMID 37850636, 2023). "Leonard I. Zon group identified SETDB1 as a cooperator of BRAF (V600E) mutation to accelerate melanoma formation." (PMID 36582533, 2022). "SETDB1 has been frequently deregulated in carcinogenesis, being implicated in the pathogenesis of gliomas, melanomas, as well as in lung, breast, gastrointestinal and ovarian tumors, where it mainly exerts an oncogenic role." (PMID 34440561, 2021). "SETDB1 expression was further associated with the BRAFV600E mutation in favor of melanoma development." (PMID 34440561, 2021). "Studies have reported that the expression of SETDB1 significantly increases the risk of melanoma, lung cancer, urothelial carcinoma, glioma, ovarian cancer, prostate cancer, breast cancer, hepatocellular carcinoma, colorectal cancer, and solid tumors." (PMID 31768101, 2019). "Several studies observed overexpression of SETDB1 in other types of tumors, like hepatocellular carcinoma and melanoma, which was associated with a poor prognosis." (PMID 31398867, 2019). "This draws parallels to a study that showed SETDB1 expression is associated with CDKN2A repression in melanoma, suggesting that SETDB1 and SETDB2 have an important role in controlling the expression of these cell cycle regulators." (PMID 30850015, 2019). "When SETDB1 was found to accelerate melanoma, two methyltransferase-deficient SETDB1 mutants also had an accelerated tumor incidence curve, likely because the complex still had methyltransferase activity." (PMID 23705022, 2013). "By combining discovery with digital expression profiling, NGS identified a novel miRNA (candidate 6), which is expressed as a part of SETDB1 transcript, a histone methyltransferase, amplified in melanoma and a candidate gene for melanoma susceptibility." (PMID 24023765, 2013). "This region encompasses the gene for histone methyltransferase SETDB1, recently identified as an oncogene and a candidate susceptibility gene in melanoma." (PMID 24119551, 2013). "For example, a common region of amplification at 1q21.2 included the histone methyltransferase SETDB1, which has been implicated in the onset of melanomas, and the apoptotic regulator BCL2L1 at 20q11 was also found recurrently amplified." (PMID 22685613, 2012). "In addition, IFN signaling and SETDB1/SETDB2 expression were enhanced upon exposure to chemotherapeutic agents or targeted therapies in melanoma, lung, and colon cancer cell lines, a phenomenon associated with therapy resistance." (PMID 39519018, 2024). "According to TCGA data, SETDB1 is amplified in 10.8% of liver cancers, 9.1% of breast cancers, 8.4% of bladder cancers, 7.4% of ovarian cancers, and 6% of uterine cancers, and mutated in about 5% of melanomas." (PMID 39583200, 2024). "Another “chromatin writers” implicated in melanoma is the SET domain bifurcated 1 (SETDB1), a member of the SUV39 family of histone lysine methyltransferases, catalyzing methylation of lysine 9 on the histone 3 which leads to epigenetically mediated gene expression silencing." (PMID 32042336, 2020).
melanoma (continued). "The SETDB1 gene is located on chromosome 1 at the level of the 1q21.3 region—a locus region with ten genes: this locus was identified as a melanoma susceptibility locus and contains two plausible genes for melanoma susceptibility: SETDB1 and Aryl Hydrocarbon Receptor Nuclear Translocator (ARNT)." (PMID 29156643, 2017). "Furthermore, novel germline alterations at the chromosomal region of 1q21.3 involving ARNT (aryl hydrocarbon receptor nuclear translocator) and SETDB1 (SET domain bifurcated histone lysine methyltransferase 1) were discovered lately as possible genetic risk factors for melanoma." (PMID 35628196, 2022). "In conclusion, SETDB1 emerges as a critical regulator in melanoma and other cancers, and its inhibition through compounds like mithramycin and paclitaxel shows promise in enhancing the efficacy of existing therapies." (PMID 39764697, 2025). "In contrast, low SETDB1 expression in melanoma (SKCM) and non‐small cell lung cancer (NSCLC) patients was associated with better radiotherapy outcomes, greater immune cell infiltration, and enhanced IFN response following SETDB1 depletion." (PMID 39764697, 2025). "In melanoma, a highly aggressive skin cancer, SETDB1 has been found to regulate key processes, such as the expression of cancer‐related secreted factors, melanocyte‐lineage differentiation, and metabolic pathways." (PMID 39764697, 2025). "Treatment with non‐specific SETDB1 inhibitors, such as mithramycin A and its analog mithralog EC‐8042, resulted in strong anti‐melanoma effects, suppressing SETDB1 expression and enhancing the efficacy of mitogen‐activated protein kinase (MAPK) inhibitors." (PMID 39764697, 2025). "Inhibition of SETDB1 in melanoma cells has led to altered transcriptomic, morphological, and functional changes, supporting its potential as a therapeutic target." (PMID 39764697, 2025). "Miramycin A and miramycin analogue EC-8042 have been reported to inhibit SETDB1 expression in melanoma to reduce the tumor growth." (PMID 39583200, 2024). "Among the genes we identified, many are known melanoma susceptibility genes including CASP8, ARNT, and OCA2 (downregulated), PARP1, SETDB1, MTAP, SLC45A2, and MC1R (upregulated), and MX2 (both up‐ and downregulated)." (PMID 38308491, 2024). "BIX-01294 (CAS 935693–62–2), a G9a HMTase inhibitor, also reduced SETDB1 expression levels in melanoma cell lines." (PMID 39583200, 2024). "Genes in cluster 8 (GSTO2, LRRC34), 9 (CLPTM1L) and 10 (CTSS, SETDB1, ANXA9, GOLPH3L, HORMAD1, PPIL3, CASP9, ALS2CR12) underlie the association between melanoma and cancers." (PMID 38308491, 2024). "For example, in murine melanoma and lung cancer models, Setdb1 knockout evoked the activation of REs and neighboring genes, leading to augmented expression of retroelement-encoded MHC I peptides targeted by T-cell cytotoxicity." (PMID 39519018, 2024). "The TCGA database shows that the SETDB1 gene is amplified in many tumours, such as liver cancer, bladder cancer, breast cancer, uterine cancer and melanomas, and in ovarian cancer, 7.4% of the SETDB1 gene is amplified." (PMID 38317200, 2024). "The contribution of SETDB1 to immune evasion was also evidenced in melanoma and colorectal mouse cell lines, however via interaction with KDM5B (lysine-specific demethylase 5B), a histone demethylase targeting H3K4me3." (PMID 39519018, 2024). "In a zebrafish melanoma model, an increase in SETDB1 expression significantly accelerated melanoma formation and transcriptionally deregulated a number of genes, including HOX genes, which are also associated with melanoma prognosis through DNAm changes." (PMID 39624739, 2024). "The inhibition of SETDB1 was found to significantly reduce cell viability in melanoma, therefore suggesting that this enzyme has the potential to become as yet another novel therapeutic target." (PMID 39624739, 2024).
melanoma (continued). "SETDB1 (KMT1E) is overexpressed in melanoma, BC, and lung cancer, is involved in stem cell maintenance and is considered an effective target for cancer therapy." (PMID 37394580, 2023). "Consistently, SETDB1 knockout in a melanoma mouse model induced the re-expression of ERV antigens presented on the surface of cells by MHC-I to induce a cytotoxic T-cell response." (PMID 37394580, 2023). "In NSCLC and melanoma patients, SETDB1 expression level is shown to be negatively correlated with radiotherapy efficacy." (PMID 38057834, 2023). "The histone methyltransferase gene SETDB1 is an important gene in the development and metastasis of melanoma in vivo." (PMID 36699463, 2022). "SETDB1 inhibition is cytotoxic to BRAFi-resistant melanoma cells, and inhibition synergizes with BRAFi and MEKi." (PMID 36497341, 2022). "To identify a cytoplasmic role for SETDB1, we first verified its cytoplasmic localization in both mouse and human melanoma cells: B16‐F1 and WM266.4 cells, respectively." (PMID 36330589, 2022). "In human cancers, an upregulation of SETDB1 is correlated with unfavorable prognoses in patients with melanoma, NPC, colorectal and several cancers." (PMID 35455671, 2022). "KDM5B-knockout melanoma cells treated with proteasome inhibitor MG132 significantly increased SETDB1 levels, suggesting a protective role for KDM5B in proteasome-dependent degradation of SETDB1." (PMID 36497341, 2022). "Most importantly, SETDB1 is amplified among the cases of human melanoma in comparison with nevus or normal skin." (PMID 36224606, 2022). "For example, KDM5B suppressed antitumor immunity and mediated immune evasion in melanoma by recruiting SETDB1 (SET domain bifurcated histone lysine methyltransferase 1) to silence retroelements." (PMID 36481938, 2022). "Previous reports revealed that SETDB1 activated AKT pathway to promote malignant melanoma progression by methylating AKT." (PMID 35184652, 2022). "In a mouse model of melanoma, SETDB1-knockout leads to the re-expression of ERV antigens, which are presented by MHC-I on the cell surface, and induces specific cytotoxic T-cell response." (PMID 35455671, 2022). "A string of recent publications have validated histone methyltransferase SETDB1 as an important regulator of melanoma immune responses." (PMID 36497341, 2022). "As an oncoprotein, overexpression of SETDB1 is widely found in pancreatic ductal adenocarcinomas, colorectal cancer, melanomas, Hela cell line of cervical cancer, lung cancer and breast cancer." (PMID 34299035, 2021). "In melanomas, SETDB1 is positively correlated with several prognostic factors, including high mitotic counts, advanced invasion depth (Clark levels), involvement of the epidermis and p16INK4 methylation." (PMID 34440561, 2021). "Mithramycin A was shown to reduce SETDB1 expression and tumor growth in melanomas with upregulated SETDB1 levels." (PMID 34440561, 2021). "While the restoration of H3K9 methylation by targeting LSD1 and JMJD2C abrogates the transition from melanocyte to melanoma triggered by driver mutations, increased H3K9 methylation induced by SETDB1 displays an oncogenic effect in an established tumor." (PMID 34924562, 2021). "Of note, to temper the impact of other H3K9 histone methyltransferases, the authors focused on melanoma cell lines with high levels of endogenous SETDB1 only." (PMID 32042336, 2020). "One gene from a recurrently amplified interval of chromosome 1q, SET domain bifurcated histone lysine methyltransferase 1 (SETDB1), significantly accelerated melanoma onset." (PMID 32455885, 2020). "SETDB1 is an oncogene in melanoma and has also been found to be over-expressed in PCa and cell lines." (PMID 33317623, 2020). "We participated in a study showing that the human SETDB1 gene is amplified in melanoma, in which SETDB1 accelerates tumorigenesis." (PMID 31398867, 2019). "HOX genes were shown to be dysregulated in the presence of upregulated SETDB1 so SETDB1 acts as an oncogene in melanoma pathogenesis." (PMID 31731811, 2019).